PKP1 (plakophilin 1)
Description:
A component of desmosome cell-cell junctions which are required for positive regulation of cellular adhesion. Plays a role in desmosome protein expression regulation and localization to the desmosomal plaque, thereby maintaining cell sheet integrity and anchorage of desmosomes to intermediate filaments. Required for localization of DSG3 and YAP1 to the cell membrane in keratinocytes in response to mechanical strain, via the formation of an interaction complex composed of DSG3, YAP1, PKP1 and YWHAG. Positively regulates differentiation of keratinocytes, potentially via promoting localization of DSG1 at desmosome cell junctions (By similarity). Required for calcium-independent development and maturation of desmosome plaques specifically at lateral cell-cell contacts in differentiating keratinocytes (By similarity). Plays a role in the maintenance of DSG3 protein abundance, DSG3 clustering and localization of these clusters to the cell membrane in keratinocytes (By similarity). May also promote keratinocyte proliferation and morphogenesis during postnatal development. Required for tight junction inside-out transepidermal barrier function of the skin (By similarity). Promotes Wnt-mediated proliferation and differentiation of ameloblasts, via facilitating TJP1/ZO-1 localization to tight junctions (By similarity). Binds single-stranded DNA (ssDNA), and may thereby play a role in sensing DNA damage and promoting cell survival. Positively regulates cap-dependent translation and as a result cell proliferation, via recruitment of EIF4A1 to the initiation complex and promotion of EIF4A1 ATPase activity. Regulates the mRNA stability and protein abundance of desmosome components PKP2, PKP3, DSC2 and DSP, potentially via its interaction with FXR1.
Synonyms: B6P; EDSFS
Tractability: Antibody: UniProt places it where antibodies can reach, with high confidence; its Gene Ontology location is reachable by antibodies, with high confidence; the Human Protein Atlas places it where antibodies can reach.
Target class: Adhesion
Gene: Protein-coding gene on chromosome 1 (201,283,452 to 201,332,993, forward strand). Ensembl gene ENSG00000081277.
Subcellular location: Cell junction, desmosome (Isoform 1); Nucleus (Isoform 2); Nucleus; Cytoplasm, perinuclear region; Cytoplasm; Cell junction, desmosome; Cell membrane; Cytoplasm, Stress granule
Subcellular location (Human Protein Atlas): Nucleoplasm; Plasma membrane
Pathways (Reactome):
Developmental Biology: Formation of the cornified envelope; Keratinization
Immune System: Neutrophil degranulation
Programmed Cell Death: Apoptotic cleavage of cell adhesion proteins
Gene Ontology:
Molecular function: DNA binding; lamin binding; protein binding; cadherin binding; intermediate filament binding; structural constituent of skin epidermis
Biological process: intermediate filament bundle assembly; negative regulation of mRNA catabolic process; positive regulation of cap-dependent translational initiation; positive regulation of cell-cell adhesion; positive regulation of gene expression; positive regulation of protein localization to membrane; positive regulation of transcription by RNA polymerase II; ameloblast differentiation; cell adhesion; cell-cell adhesion; desmosome assembly; positive regulation of keratinocyte differentiation; positive regulation of protein localization to plasma membrane; signal transduction; desmosome maintenance; transepithelial water transport
Cellular component: cytoplasm; desmosome; nuclear stress granule; nucleus; perinuclear region of cytoplasm; plasma membrane; adherens junction; cornified envelope; ficolin-1-rich granule membrane; intermediate filament; cytoplasmic stress granule
Genetic constraint (gnomAD): Loss-of-function variants: 25 observed, 70.01 expected, observed/expected ratio (o/e) 0.36, 90% interval 0.26 to 0.5. The upper end of that interval is the gene's LOEUF score, 0.5, which puts it in group 2 of 6, group 1 being the genes least tolerant of losing a copy. Missense variants: 954 observed, 976.48 expected, observed/expected ratio (o/e) 0.98, 90% interval 0.93 to 1.03. Synonymous variants: 401 observed, 393.97 expected, observed/expected ratio (o/e) 1.02, 90% interval 0.94 to 1.11.
Homologues: Orthologues: chimpanzee PKP1 (100% identical), macaque PKP1 (99% identical), dog PKP1 (95% identical), mouse Pkp1 (95% identical), rat Pkp1 (95% identical), guinea pig PKP1 (95% identical), pig PKP1 (93% identical), rabbit PKP1 (88% identical), zebrafish pkp1b (34% identical), tropical clawed frog pkp1 (26% identical), Caenorhabditis elegans jac-1 (22% identical), Drosophila melanogaster p120ctn (21% identical), and 1 more. Paralogues in human: PKP2 (33% identical), CTNND2 (29% identical), PKP4 (29% identical), ARVCF (28% identical), PKP3 (27% identical), CTNND1 (25% identical).
Diseases named in the same sentence as PKP1 in open-access papers:
PKP1 is named in the same sentence as 45 diseases in open-access papers, as found by Europe PMC text mining. Sharing a sentence is not in itself a finding about the gene and the disease. The quoted sentences say what the papers report.
ectodermal dysplasia (13 papers, 2006 to 2025). "Mutation of PKP1 can cause the skin-fragility ectodermal-dysplasia syndrome, with sparse eyelashes and eyebrows and loose scalp hair." (PMID 36423088, 2022). "PKP1 mutations lead to ectodermal dysplasia/skin fragility syndrome, which includes abnormalities of both skin and hair development." (PMID 36342464, 2022). "PKP1 has been implicated in ectodermal dysplasia/skin fragility syndrome, which is associated with tooth anomalies such as missing teeth and enamel hypoplasia." (PMID 27015268, 2016). "Mutations in the Pkp1 gene result in ectodermal dysplasia/skin fragility syndrome, which affect skin, hair, and nails." (PMID 27015268, 2016). "It was previously reported that a mutation in the Pkp1 gene results in ectodermal dysplasia/skin fragility syndrome." (PMID 27015268, 2016). "Altogether, the clinical and pathological findings, along with the PKP1 mutation, were consistent with the diagnosis of ectodermal dysplasia-skin fragility syndrome with plakophilin-1 deficiency." (PMID 22384142, 2012). "Moreover, a mutation in the plakophilin 1 gene (PKP1) resulting in PKP1 protein deficiency in the skin causes ectodermal dysplasia-skin fragility syndrome in Chesapeake Bay retriever dogs." (PMID 27357287, 2016). "Increased skin fragility was accompanied by a decrease in the number and size of basally disposed desmosomes within the ectoderm, consistent with prior Pkp3 depletion studies, and studies of patients with Pkp1 mutations that exhibit skin fragility ectodermal-dysplasia." (PMID 22496792, 2012). "Among the subtypes of EB simplex, the suprabasal variants now include lethal acantholytic EB due to mutations of the gene encoding desmoplakin, the ectodermal dysplasia-skin fragility syndrome (ED-SFS) with plakophilin-1 (PKP1) deficiency and EBS superficialis of unknown genetic cause." (PMID 22384142, 2012). "Our findings provide insight into the basic function of PKP1 and suggest possible applications in tooth germ regeneration, as well as show it to be a potential target in treatment of diseases such as ectodermal dysplasia/skin fragility syndrome." (PMID 27015268, 2016). "Mutations found in PKP1, DSG1, PG, or DP give rise to symptoms typical of ectodermal dysplasias, while autoantibodies against desmosomal proteins induce Pemphigus Vulgaris or Pemphigus Foliaceus, accompanied by blisters in the oral mucosa and/or skin." (PMID 20628490, 2010).
lung carcinoma (8 papers, 2020 to 2025). "Similarly, lung cancer cell lines exhibit PKP1 downregulation associated with promoter methylation, emphasizing the recurrent nature of epigenetic regulation in carcinogenesis." (PMID 41458151, 2025). "In breast and lung cancer, overexpression of PKP1/DSC2 activates the PI3K/AKT/Bcl-2 pathway, promoting CTC cluster formation." (PMID 41458151, 2025). "In fact, high levels of PKP1 have been detected in patients with breast and lung cancers, and such a high expression has been correlated with a lower survival rate and a worse disease progression in patients." (PMID 38785968, 2024). "In patients with breast and lung cancers, the presence of high levels of PKP1 has been described, and such high expression has been correlated with a lower survival rate." (PMID 38785968, 2024). "Moreover, the fact that the expression of PKP1 is high in fibroblasts and that PKP1 has been observed to be expressed in high amounts in lung cancers made the MRC-5 cell line a suitable candidate to check for the interaction between RYBP and PKP1." (PMID 38785968, 2024). "Furthermore, higher expression of DSC2 and PKP1 was correlated with lower overall survival and worse disease progression in patients with breast and lung cancer." (PMID 36927383, 2023). "PKP1 has been shown to be downregulated in lung cancer and predict favorable clinical outcomes." (PMID 36186467, 2022). "The decrease of DSG1, DSC2, DSC3, DSG3, PG, PKP1-3, and DSP expression associated with poor prognosis in patients with multiple cancers such as head and neck cancer, colon cancer, skin cancer, esophageal cancer, lung cancer, cervical cancer, and gastric cancer." (PMID 34203070, 2021). "It has been shown that RYBP inhibits the progression and metastasis of lung cancer by suppressing EGFR signaling and EMT, and high levels of PKP1 are important to maintain a high expression of vimentin, which is a key regulator of EMT and metastasis." (PMID 38785968, 2024). "And, in a more recent study, breast and lung cancer cells resistant to shear stress revealed an up-regulation of DSC2 and PKP1, leading to more CTC cluster formation and enhanced cell survival in circulation via activation of the PI3K/AKT/Bcl-2 pathway." (PMID 36927383, 2023).
melanoma (7 papers, 2020 to 2025). A malignant, usually aggressive tumor composed of atypical, neoplastic melanocytes. "In conclusion, we reported the association of HRGs with patient prognosis in melanoma and screened for novel gene signatures, including FBP1, NDRG1, GPI, IER3, B4GALNT2, BGN, PKP1, and EDN2." (PMID 37422626, 2023). "Given that FLG, PKP1, and TGM1 are ECM related, their association with CTNND1 raises the possibility that altered adhesion dynamics converge with ECM remodeling to promote melanoma progression." (PMID 41321310, 2025). "As the expression levels of DSC2, DSC3, DSG1, KRT6B, PKP1, and PKP3 increased, the overall survival time of trunk subtype melanoma patients significantly decreased." (PMID 38660305, 2024). "Our analysis, grounded in WGCNA and PPI networks, identified six genes (DSC2, DSC3, DSG1, KRT6B, PKP1, PKP3) with pivotal roles in melanoma’s oxidative stress response and immune infiltration." (PMID 38660305, 2024). "Through LASSO regression, the following six genes were specifically identified to have an irreplaceable prognostic effect on melanoma patients: MLKL, PARVA, PKP1, PSME1, RNF114, and TROAP." (PMID 37127623, 2023). "Among them, some hub genes had been found to be related to the production and metastasis of melanoma, such as SPRR1 and PKP1." (PMID 33240619, 2020). "The results indicate that in trunk subtype melanomas, the protein expression levels of DSC2, DSC3, DSG1, KRT6B, PKP1, and PKP3 are significantly higher than those in adjacent normal samples, suggesting the crucial roles of these central genes in SKCM progression." (PMID 38660305, 2024). "However, in other subtype melanoma patients, only DSG1 and PKP1 exhibit significantly elevated protein expression levels compared to adjacent normal samples, with no observed differences in other genes between tumor and adjacent normal samples." (PMID 38660305, 2024). "PKP1 and TROAP were commonly amplified in melanoma patients." (PMID 37127623, 2023). "In TCGA-SKCM, we found that the collective up-regulation of JUP, PKP1, and PKP3 could define a distinct catenin subgroup in melanoma (C2), which possesses poorer survival and more aggressive clinical features compared to another subgroup (C1)." (PMID 37924160, 2023). "Finally, six LLPS-related genes (MLKL, PARVA, PKP1, PSME1, RNF114, and TROAP) constitute the prognostic model and predicted clinical outcomes in melanoma patients." (PMID 37127623, 2023). "Interestingly, there are 2 RNA expression patterns of catenins in TCGA-SKCM, where PKP1, JUP, PKP3 belong to the same group and are deleterious for survival in melanoma patients." (PMID 37924160, 2023).
breast carcinoma (4 papers, 2022 to 2025). "On the other hand, PKP1 appears implicated in the development of prostate, lung, and breast cancers, among others." (PMID 38785968, 2024). "Desmoglein 2, desmocollin 2 (DSC2) and plakophilin 1 (PKP1) have been recently linked to an increased metastatic potential of breast cancer cells by promoting cell clustering and enhanced survival during the tumour cell dissemination process." (PMID 36927383, 2023). "In breast cancer models, PKP1 facilitates the formation of circulating tumor cell (CTC) cluster via activation of the PI3K/AKT/Bcl-2 pathway, thereby enhancing metastatic survival in the bloodstream." (PMID 41458151, 2025). "Conversely, PKP1 exhibits oncogenic properties in nasopharyngeal and breast cancers." (PMID 41458151, 2025). "Moreover, a genome-wide association study (GWAS) of breast cancer declared identification of 65 novel loci associated remarkably with a high risk of breast cancer at P < 5 × 10− 8 such as FES, MAP 3 K11, CLK2, GRK7, USP25, DFFA, PKP1, and ZKSCAN3." (PMID 35650591, 2022). "At the post-transcriptional level, miR-328a mitigates the oncogenic effects of PKP1 by directly targeting it, while the lncRNA APPAT acts as a miR-328a sponge to modulate PKP1 expression in breast cancer." (PMID 41458151, 2025).
esophageal squamous cell carcinoma (3 papers, 2010 to 2025). Esophageal squamous cell carcinoma (ESCC) is a type of esophageal carcinoma (EC) that can affect any part of the esophagus, but is usually located in the upper or middle third. "In esophageal SCC cell lines, the expression of PKP1 and its associated gene signatures have been significantly correlated with sensitivity to various anti-cancer drugs, suggesting that PKP1 may serve as a potential predictive biomarker for chemotherapy response." (PMID 41458151, 2025). "Beyond its individual prognostic significance, PKP1 has been recently recognized as a crucial component of a robust multi-gene prognostic signature for esophageal SCC." (PMID 41458151, 2025). "In esophageal SCC, PKP1 is a vital component of a four-gene prognostic signature (CCND1-PKP1-JUP-ANKRD12), where its low expression is independently predictive of poorer overall survival." (PMID 41458151, 2025).
metastatic melanoma (3 papers, 2020 to 2025). A melanoma that has spread from its primary site to another anatomic site. "Plakophilin 1 (PKP1) is overexpressed in metastatic melanoma and is a factor of poor prognosis in patients with CM, suggesting a link between PKP1 gene expression and immune efficacy." (PMID 37422626, 2023). "Beyond E-cadherin, we observed enrichment of proteins that preferentially associate with nonpalmitoylated CTNND1, including filaggrin (FLG), plakophilin-1 (PKP1), and transglutaminase 1 (TGM1), all linked to poor clinical outcomes in metastatic melanoma." (PMID 41321310, 2025).
prostate carcinoma (3 papers, 2017 to 2023). A carcinoma that arises from epithelial cells of the prostate gland. "PKP1 associates with eukaryotic translation initiation factor 4A1 to stimulate protein translation and loss of PKP1 is linked to prostate cancer proliferation." (PMID 29052507, 2017). "Alterations in PKP1 are present in patients with skin fragility syndrome and because of its tumor-suppressing role, is inhibited in prostate cancer." (PMID 37109658, 2023). "In recent years, many studies have shown that PKP1/2/3 played a well-established role in the occurrence, development, invasion and metastasis of various malignancy, including breast cancer, prostate cancer, gastric cancer." (PMID 33088217, 2020).
Barrett esophagus (2 papers, 2025). Esophageal lesion lined with columnar metaplastic epithelium which is flat or villiform. "The loss of membrane-associated PKP1 is a characteristic feature of carcinogenesis, as observed in precancerous Barrett’s esophagus and EAC." (PMID 41458151, 2025). "Loss of PKP1 promoter methylation could lead to the transition of Barrett's esophagus to esophageal cancer through a decrease in desmosome assembly and an increase in cell motility." (PMID 40836964, 2025). "For instance, Barrett’s esophagus and EAC exhibit hypermethylated PKP1 promoters with concomitant expression loss." (PMID 41458151, 2025). "Similarly, during the progression from Barrett’s esophagus to adenocarcinoma, hypermethylation of the PKP1 promoter results in its silencing, which contributes to desmosome destabilization and tumorigenesis." (PMID 41458151, 2025). "Furthermore, PKP1 demonstrates potential in the early detection of cancer, as evidenced by an increase in promoter methylation frequency from 12.8% in Barrett’s esophagus to 33.3% in high-grade dysplasia and EAC (p < 0.05), highlighting its value as an epigenetic biomarker for risk stratification." (PMID 41458151, 2025).
hypotrichosis (2 papers, 2017 to 2025). A congenital condition, usually due to genetic aberrations, that is characterized by a lack of hair growth on the head and/or body. "Mutations in Plakophilin 1 (PKP1) cause an inherited disease impacting ectodermal structures, and patients display hypotrichosis, nail dystrophy, and skin fragility." (PMID 29176608, 2017).
keloid (2 papers, 2016 to 2022). An irregularly shaped, elevated mark on the skin caused by deposits of excessive amounts of collagen during wound healing. "Moreover, several proteins that play a role in cell junctions were also downregulated in keloids, including EVPL, PPL, DSP, PKP1, PKP3, DSC1, DSG1, and FLG." (PMID 35435317, 2022).
Nail dystrophy (2 papers, 2017 to 2025). Onychodystrophy (nail dystrophy) refers to nail changes apart from changes of the color (nail dyschromia) and involves partial or complete disruption of the various keratinous layers of the nail plate. "ED-SF syndrome, an autosomal recessive disorder caused by PKP1 mutations, presents with fragile skin, chronic lip inflammation, palmoplantar keratoderma, abnormal hair growth, and nail dystrophy." (PMID 41426600, 2025).
nasopharyngeal carcinoma (2 papers, 2022 to 2025). A carcinoma arising from the nasopharyngeal epithelium. "In nasopharyngeal carcinoma (NPC), overexpression of PKP1 is associated with reduced progression-free survival, as it impairs B-cell proliferation through pathways mediated by myeloid-derived suppressor cells (MDSC)." (PMID 41458151, 2025).
oropharyngeal squamous cell carcinoma (2 papers, 2011 to 2020). "PKP1 was inversely associated with the histological grade of human primary oropharyngeal squamous cell carcinoma." (PMID 32299152, 2020). "PKP1 immunoreactivity inversely correlates with tumor grade in oropharyngeal squamous cell carcinoma (SCC) and adenocarcinoma." (PMID 21194493, 2011).
arrhythmogenic right ventricular cardiomyopathy (1 paper, 2020). "In humans, mutation of PKP1 gene caused a skin fragility syndrome characterized by ectodermal dysplasia and skin fragility, mutation of PKP2 gene was closely associated with arrhythmogenic right ventricular cardiomyopathy(ARVC)." (PMID 33088217, 2020).
breast adenocarcinoma (1 paper, 2024). "In the breast adenocarcinoma, the expression of both proteins was found mostly in the cytosol, suggesting that contrary to MRC-5, the interaction of PKP1 and RYBP may occur in the cytosol." (PMID 38785968, 2024).
cardiomyopathy (1 paper, 2016). A disease of the heart muscle or myocardium proper. "Upregulated genes linked to cardiomyopathy included Pkp2, Dst, Dsg2 and Jup; downregulated genes included Pkp1, Dsg1a, Pkp4, Vcl, Gja1 and Ctnna1." (PMID 26935106, 2016).